S100A7 (S100 calcium binding protein A7)
Diseases named in the same sentence as S100A7 in open-access papers (continued):
Sharing a sentence is not in itself a finding about the gene and the disease.
Trichiasis (4 papers, 2012 to 2018). Inversion and rubbing of the eyelashes against the globe of the eye. "In an un-conditional logistic regression model for recurrent trichiasis and baseline factors, only conjunctival inflammation and S100A7 expression were significantly associated with subsequent recurrence." (PMID 23285311, 2012). "Recurrent trichiasis remained significantly associated with increased expression of S100A7 after adjusting for other factors in these models, both before and after surgery." (PMID 23285311, 2012). "The observation that increased expression of S100A7 was consistently associated with recurrent trichiasis indicates that it may have a role in this disease process." (PMID 23285311, 2012). "This identified a variety of pro-inflammatory (IL1B, TNFA, S100A7, CXCL5, NOS2A) and tissue remodelling factors (MMP7, MMP9 and MMP12), which were associated with conjunctival scarring and trichiasis before surgery." (PMID 23285311, 2012). "In the present study the only gene found to have consistently increased conjunctival expression (both before and after surgery) in individuals who developed recurrent trichiasis was S100A7 (Psoriasin)." (PMID 23285311, 2012). "However, it is difficult to determine in this longitudinal study following trichiasis surgery the potential contribution that S100A7 might make to the pathophysiology of recurrent trichiasis or progressive conjunctival scarring in general." (PMID 23285311, 2012). "By staining tissue sections with dyes and specific antibodies, pro-inflammatory signaling molecules IL-1β and S100A7 and pro-fibrotic growth factor CTGF were found to be more highly expressed in individuals with trichiasis." (PMID 27249027, 2016).
bladder squamous cell carcinoma (3 papers, 2010 to 2023). A squamous cell carcinoma of the bladder arising from metaplastic epithelium. "S100A7 plays a crucial role in the innate immune system and has been linked to bladder squamous cell carcinoma." (PMID 36807337, 2023). "S100A7 overexpression showed association with well differentiated squamous cell carcinoma of the bladder in comparison the less differentiated tumors." (PMID 20689826, 2010).
breast adenocarcinoma (3 papers, 2005 to 2019). "Subsequent studies have shown that upregulation of S100A7 is detected in nearly all types of SCC tissues as well as adenocarcinomas of the breast." (PMID 28177901, 2017). "Third, breast adenocarcinoma MDA-MB-468 cells highly expressed S100A7, whereas MDA-MB-231 cells did not express S100A7 and formed poorly differentiated tumors in ALS-treated BALB/c mice." (PMID 28177901, 2017).
cutaneous melanoma (3 papers, 2022 to 2024). A primary melanoma arising from atypical melanocytes in the skin. "The significant levels of S100A7 expression in primary cutaneous melanoma and the ease in detection in urine samples make it a promising diagnostic classifier." (PMID 36553569, 2022). "More importantly, higher levels of S100A7 were detected in the urine of cutaneous melanoma patients compared to a control group." (PMID 36553569, 2022). "S100A7 displayed a remarkably lower level in tumor tissues of skin cutaneous melanoma (SKCM) than in the corresponding normal tissues." (PMID 35205150, 2022). "A follow-up analysis of PPI identified S100A7 as a hub gene in primary cutaneous melanoma." (PMID 36553569, 2022). "However, a low expression of S100A7 was found in skin melanoma, which is in line with a previous study." (PMID 35205150, 2022). "S100A7 expression was closely related to the overall survival of patients with skin cutaneous melanoma, kidney renal clear cell carcinoma, liver hepatocellular carcinoma, and the disease-specific survival of patients with kidney renal clear cell carcinoma and skin cutaneous melanoma." (PMID 38499391, 2024).
dermatitis (3 papers, 2005 to 2025). An inflammatory process affecting the skin. "We also found evidence of expression changes related to skin lesions/dermatitis and the process of wound healing including the activity of the gene S100A7." (PMID 40599378, 2025). "Notably, S100A7 (psoriasin) is overexpressed in hyperproliferative skin disorders, modulating cytokine and chemokine production." (PMID 39769332, 2024). "Our current data from a model of mouse skin inflammation is also consistent with such a role, since a significant upregulation in mouse S100A7/psoriasin expression occurs simultaneously with the acute phase of skin inflammation after application of croton oil to the mouse tail skin." (PMID 15717926, 2005).
endometrial cancer (3 papers, 2022 to 2024). Primary or metastatic malignant neoplasm involving the endometrium (mucous membrane that lines the endometrial cavity). "Based on this analysis, CSTA and S100A7 were confirmed to discriminate early-stage endometrial cancer from controls with AUC values of 0.75 (0.64–0.85) and 0.73 (0.63–0.83), respectively." (PMID 36807337, 2023). "A four-marker panel comprising CSTA, S100A7, MMP9 and SERPINA10 predicted endometrial cancer with an AUC of 0.84 (0.77–0.92), sensitivity of 72.2%, specificity of 87.8%, NPV of 86.7% and PPV of 74.1%." (PMID 36807337, 2023). "Urine SPRR1B, S100A7, CALML3 and TXN were also found to have potential as endometrial cancer biomarkers." (PMID 36807337, 2023).
gastric cancer (3 papers, 2008 to 2022). A primary or metastatic malignant neoplasm involving the stomach. "In addition, a remarkable upregulation of S100A7 was found in breast, lung, brain, colorectal and gastric cancers compared to normal controls, based on the pooling analysis of various studies in the Oncomine database." (PMID 35205150, 2022). "Among them, four genes, including S100A2, S100A4, S100A7 and S100A10, were reported to overexpressed in gastric cancer previously." (PMID 18793447, 2008). "In addition, molecular analysis has revealed that several S100s, including S100A2, S100A4, S100A7 and S100A10, exhibit altered expression levels in gastric cancer." (PMID 18793447, 2008). "S100A4, S100A6 and S100A7 were shown to be upregulated in gastric cancer in only one dataset but did not exist in the other two datasets." (PMID 18793447, 2008).
head and neck cancer (3 papers, 2010 to 2016). A primary or metastatic malignant neoplasm affecting the head and neck. "Nuclear accumulation of S100A7 has been reported to be associated with a poor prognosis in head and neck cancer." (PMID 23451142, 2013). "Apart from S100A7, aberrant expression of other S100A family members is emerging as an important event in head and neck cancers." (PMID 27297407, 2016).
keloid (3 papers, 2020 to 2025). An irregularly shaped, elevated mark on the skin caused by deposits of excessive amounts of collagen during wound healing. "We found that cutaneous appendages, such as sebaceous glands and hair follicles in keloid tissues, were stained with S100A7." (PMID 38622256, 2024). "Of those, six genes (i.e., OPCML, S100A7, S100 calcium binding protein A8 [S100A8], KANK4, PTPRD, tenascin XB [TNXB]) were significantly differentially expressed between keloid and immature scar samples." (PMID 38622256, 2024). "S100A7 and S100A8 exhibited the second and third greatest upregulation in keloids, respectively." (PMID 38622256, 2024).
leukoplakia (3 papers, 2010 to 2022). A white patch or plaque on a mucous membrane that cannot be characterized clinically or pathologically as any other disease. "Nevertheless, this finding warrants confirmation in a longitudinal follow-up study of patients with oral leukoplakia lesions, to establish a possible link between nuclear S100A7 expression and risk of cancer development." (PMID 20689826, 2010). "Three proteins—CD44, S100A7, and S100P—were significantly different in dysplastic leukoplakia compared to the normal cohort, with CD44 showing the highest sensitivity." (PMID 34830890, 2021). "Of the 166 oral leukoplakia lesions analyzed, 97 cases (58.4%) showed significant increase in cytoplasmic S100A7 immunostaining (p<0.001, Odds ratio (OR) = 7.4, 95% CI = 3.9−13.7)." (PMID 20689826, 2010).
lymph node metastasis (3 papers, 2017 to 2024). "In concordance with the results of our in vitro study, S100A7 was positively correlated with malignant markers such as higher Ki-67 LI, advanced clinical stage, higher histological grade, and the presence of lymph node metastasis." (PMID 28629450, 2017). "The statistic results showed that S100A7 immunoreactivity significantly correlated with histologic subtype (P =0.017), tumor grade (P = 0.007), and lymph node metastasis (P = 0.033)." (PMID 28212564, 2017). "Our IHC results indicated that S100A7 expression is significantly correlated with lymph node metastasis." (PMID 28212564, 2017). "S100A7 (psoriasin), a member of the epidermal differentiation complex, is widely overexpressed in invasive ER negative breast cancer especially in lymph node metastasis." (PMID 39830522, 2024).
osteosarcoma (3 papers, 2015 to 2017). A usually aggressive malignant bone-forming mesenchymal neoplasm, predominantly affecting adolescents and young adults. "S100A7 was found to be secreted, extracellular S100A7 promotes migration and invasion osteosarcoma cells via RAGE." (PMID 28212564, 2017). "This is relevant to the observation that S100A7 promotes the migration and invasion of osteosarcoma cells via the receptor for advanced glycation end products." (PMID 26510912, 2015).
allergic rhinitis (2 papers, 2008 to 2012). Inflammation of the nasal mucous membranes caused by an IgE-mediated response to external allergens. "The aims of this study were to describe genetic variation in S100A7 and search for associations between this variation and allergic rhinitis." (PMID 18373864, 2008). "The aim of the present study was to explore the expression and regulation of S100A7 in seasonal allergic rhinitis (SAR)." (PMID 22230654, 2012). "S100A7 protein levels are decreased in nasal lavage fluid from individuals with ongoing allergic rhinitis, suggesting a role for S100A7 in allergic airway inflammation." (PMID 18373864, 2008). "One of these proteins, S100A7, also called psoriasin, appeared to be of special interest since it was found to be markedly down-regulated in patients with symptomatic allergic rhinitis." (PMID 18373864, 2008). "The idea that S100A7 might have a role in allergic rhinitis is supported by its potent chemotactic effects on T lymphocytes and neutrophils." (PMID 18373864, 2008). "This corresponds to a p-value of 0.033 in a one-sided sign-test, and further strengthens the hypothesis that genetic variation in S100A7 is related to allergic rhinitis." (PMID 18373864, 2008). "We have previously shown lower levels of S100A7 in nasal lavage (NAL) fluid from patients with pollen-induced seasonal allergic rhinitis (SAR) compared to non-allergic controls, along with lower S100A7 mRNA levels in tonsils obtained from allergic as compared to healthy donors." (PMID 22230654, 2012).
and large cell carcinomas (2 papers, 2013 to 2025). "Selective expression of S100A7 in lung SCC and large cell carcinomas has been demonstrated, but not in AC or small cell carcinomas." (PMID 23451142, 2013).
asthma (2 papers, 2021 to 2023). "In asthma, S100A7 plays a role in the interplay between the proinflammatory cytokine IFN-γ and IL-22." (PMID 34239729, 2021). "We first documented baseline expression of S100A7, S100A8 and S100A9 genes in severe asthma and compared to BECs obtained from healthy controls." (PMID 37996952, 2023). "Epithelial expression of S100A7 and S100A8 pre-BT negatively correlated with ACCS score (r = − 0.6; p-value = 0.03 and r = − 0.7; p-value = 0.006 respectively) suggesting that higher expression of these proteins might indicate a poorer asthma control." (PMID 37996952, 2023).
carcinoma in situ (2 papers, 2011 to 2014). "For instance, four patient samples had ICD9 code 233.1 (carcinoma in situ) and three of them (samples #109, #110, and #116) had S100A7 genes up-regulated and another set (samples #110, #111, and #116) had KLK6 up-regulated in normal to LGSIL pairs." (PMID 25505737, 2014). "In a study of the serial analysis gene expression (SAGE) of human larynx tumor tissue several differentially expressed genes were identified, among them, the up-regulation of the S100A7 gene belonging to a family of calcium-binding proteins." (PMID 22082027, 2011).
cervical (2 papers, 2014 to 2017). "And S100A7 overexpression might serve as a useful marker for estimating the risk of cervical dysplastic lesions progressing to malignancy." (PMID 28212564, 2017). "In particular, S100A7 and KLK6 genes were differentially expressed during progression from normal tissue to LGSIL in 3/6 samples and could be key members of signature networks in cervical pre-cancer progression." (PMID 25505737, 2014).
chronic periodontitis (2 papers, 2013 to 2021). A chronic inflammatory process that affects the tissues that surround and support the teeth. "In another study, cathepsin G, cathelicidin antimicrobial peptide, protein S100-A7, 14-3-3 protein sigma and vitamin D-binding were found more frequently in chronic periodontitis when compared to healthy subjects." (PMID 24098404, 2013). "The concentrations of interleukins and S100A7 were similar in psoriatic patients with or without periodontitis vs. healthy controls." (PMID 33531183, 2021).
chronic rhinosinusitis (2 papers, 2012 to 2020). Chronic form of sinusitis. "Richer and collaborators (2009) showed a decreased expression of S100A7, S100A8, S100A9, and SPINK5 genes in the airway mucosal epithelium of people with chronic rhinosinusitis, which they associated with a defective epithelial barrier in this condition." (PMID 32735560, 2020).
dermatophytosis (2 papers, 2021 to 2022). A common fungal infection of the stratum corneum of the skin, hair, or nails by a dermatophyte. "It is worth noting that S100A7 deficiency is involved in the lower infiltration of Th17 cells, which participates in the pathogenesis of dermatophytosis-prone adult T-cell leukemia/lymphoma." (PMID 35205150, 2022). "Further, the epidermal expression of hBD-2, LL-37, and S100A7/psoriasin is decreased in patients with ATLL and dermatophytosis, indicating that the secretion of Th17-mediated antimicrobial peptides by keratinocytes is reduced, leading to the frequent occurrences of dermatophytosis." (PMID 34071562, 2021).
ductal carcinoma in situ (2 papers, 2012 to 2013). "S100A7 is a member of the S100 family of proteins, which have been associated with preinvasive ductal carcinoma in situ (DCIS)." (PMID 23618129, 2013).
endometriosis (2 papers, 2021 to 2022). The growth of functional endometrial tissue in anatomic sites outside the uterine body. "Several members of the S100 protein family were under-expressed in the eutopic endometrium of women with endometriosis during the mid-secretory phase: S100A7, S100A8, S100A9, and S100A12." (PMID 35204508, 2022). "Previous studies showed that S100A7 promoted the development of endometriosis by activating NF-kappaB signaling pathway." (PMID 34522169, 2021).
fungal infection (2 papers, 2024 to 2025). "We speculate that the upregulation of CD82 and S100A7 in CAL 27 is part of the cells’ reaction to a fungal infection." (PMID 38473906, 2024). "Notably, the S100A7 gene was upregulated in persisting little brown bat populations compared to unexposed populations, supporting findings of past work demonstrating S100A7 activity in bat tissue with active fungal infection." (PMID 40599378, 2025).
liver cancer (2 papers, 2022). An epithelial or non-epithelial malignant neoplasm that arises from the liver. "Members of the S100 calcium binding protein family, namely, S100A7, S100A8, S100A9, and S100A10, exert a momentous function in tumor growth and metastasis, such as breast and liver cancer." (PMID 36421685, 2022).
metastatic disease (2 papers, 2007 to 2010). "The data suggest that abundant expression of CEACAM7 and S100A7 collectively, are unique to cervical tissue and have the potential to serve as useful biomarkers in identifying origins of metastatic disease." (PMID 17543121, 2007).
oral lichen planus (2 papers, 2024 to 2025). Oral lichen planus is a chronic inflammatory oral condition of unknown aetiology characterized by T-cell-mediated chronic immune response and abnormal epithelial keratinization cycle. "However, the function of S100A7 in oral lichen planus (OLP), a chronic inflammatory disease, remains unclear." (PMID 40560736, 2025). "The differential expression of AMPs in oral lichen planus patients, characterized by reduced levels of S100A8 and S100A9 and increased levels of S100A7, suggests alterations in the chemical barrier that may enhance susceptibility to oral infections and inflammation." (PMID 38750317, 2024).
Parkinson disease (2 papers, 2009 to 2025). A progressive degenerative disorder of the central nervous system characterized by loss of dopamine producing neurons in the substantia nigra and the presence of Lewy bodies in the substantia nigra and locus coeruleus. "Transcriptomic and proteomic analyses revealed significantly altered levels of transcripts (RN7SL3, RN7SL1, miR19B2, SYF2P2, and S100A7) and proteins (psoriasin [S100A7] and dystroglycan 1) in patients with MSA-P compared with those with Parkinson’s disease." (PMID 41439986, 2025).
Skin ulcer (2 papers, 2020 to 2024). A discontinuity of the skin exhibiting complete loss of the epidermis and often portions of the dermis and even subcutaneous fat. "In addition, S100A7 was shown to be significantly upregulated in the skin ulcers of patients with DFU." (PMID 38434138, 2024).
squamous cell tumors (2 papers, 2008 to 2017). "Enhanced expression of S100A7 has been recognized in psoriatic skin lesions, as well as in squamous cell tumors of the skin, mouth, lung, and breast." (PMID 28629450, 2017). "S100A7 is a small calcium binding protein, which has been shown to be differentially expressed in psoriatic skin lesions, as well as in squamous cell tumors of the skin, lung and breast." (PMID 18320059, 2008).
tongue tumor (2 papers, 2016 to 2018). "Forced expression of S100A7 is accompanied by repressed cell proliferation and tumor progression in orthotopic tongue tumor model." (PMID 27297407, 2016).
Arthritis (1 paper, 2024). Inflammation of a joint. "Similarly, S100A7 polymorphisms regulating gene expression might affect RA susceptibility, severity, and risk of early onset of arthritis, potentially as well as the therapeutic response to either glucocorticoid or adrenocorticotrophic hormone." (PMID 39600762, 2024).
bladder urothelial carcinoma (1 paper, 2024). "What’s more, S100A7 expression was closely related to the overall survival of patients with bladder urothelial carcinoma." (PMID 38499391, 2024).
Candida infection (1 paper, 2023). "In this study, Candida infection also led to the induction of S100A7 gene expression, and it is the first to show that CAP treatment of the infected skin models resulted in reduced S100A7 transcript levels, which were associated with reduction in hyphal growth." (PMID 37237836, 2023).
carotid atherosclerosis (1 paper, 2019). A thickening and loss of elasticity of the walls of carotid arteries that occur with formation of atherosclerotic plaques. "In human, several S100 proteins, including S100A7, S100A8, S100A9, and S100A12, are linked with the severity of coronary and carotid atherosclerosis." (PMID 30886860, 2019).
cervical tumor (1 paper, 2024). "S100A7 plays a role in the initial stages of cervical tumor progression." (PMID 39140365, 2024).
cholesteatoma (1 paper, 2014). A pathologic process characterized by the proliferation of keratinizing squamous epithelium resulting in the accumulation of keratin and cells in the middle ear and/or mastoid. "Cholesteatoma contained high levels of pro-inflammatory S100 proteins, such as S100A7A and S100A7." (PMID 25093596, 2014).